LEISA1 (lncRNA enhancing IL-6/STAT3 signaling activation 1)
Synonyms: LEISA; formerly NAV2-AS6
Gene: Long non-coding RNA gene on chromosome 11 (19,710,934 to 19,712,619, reverse strand). Ensembl gene ENSG00000270607.
Diseases named in the same sentence as LEISA1 in open-access papers:
LEISA1 is named in the same sentence as 2 diseases in open-access papers, as found by Europe PMC text mining. Sharing a sentence is not in itself a finding about the gene and the disease.
LEISA1 shares sentences with these, for which no sentence is quoted: lung adenocarcinoma (1 paper); tumor (1).